ABCC8 (ATP binding cassette subfamily C member 8)
Diseases named in the same sentence as ABCC8 in open-access papers (continued):
Sharing a sentence is not in itself a finding about the gene and the disease.
diabetes (continued). "We analysed the most relevant common neonatal diabetes genes (KCNJ11, ABCC8, INS) to exclude monogenic diabetes in infancy-onset diabetes (n = 8 patients with manifestation before age 12 months)." (PMID 28534863, 2017). "The genes ABCC8 and KCNJ11 have received intense focus in type 2 diabetes mellitus (T2DM) research over the past two decades." (PMID 25955821, 2015). "There were six patients with the INS variant, four with the ABCC8 variant and one with the HNF1B variant without a family history of diabetes." (PMID 40303944, 2025). "Initial targeted sequencing of neonatal diabetes-associated genes (including KCNJ11, ABCC8, INS, and the 6q24 locus) yielded negative results." (PMID 41393705, 2025). "Abcc8 and Kcnj11 knockout mice, both of which lack functional KATP channels and exhibit a sustained elevation in [Ca2+]i, display mild hypoglycemia as young animals but develop diabetes as they age." (PMID 39015185, 2024). "ABCC8, KCNJ11 and INS are the most commonly involved genes in this age group and maybe present on a generic monogenic diabetes panel." (PMID 37033247, 2023). "The spectrum of causative genes (PTF1A, GLIS3, WFS1, INSR, SLC29A3, ZNF808, ABCC8, INS) is markedly different from the monogenic diabetes genes seen in non-consanguineous cohorts, and also different from those seen in other consanguineous populations." (PMID 37897565, 2023). "The phenotypes of ABCC8-NNDM were variable and could also present with early hyperinsulinemia followed by reduced insulin secretion, progressing to diabetes later." (PMID 34631896, 2021). "No other clear clinical manifestation besides diabetes has been described for patients with heterozygous mutations in KLF11 (MODY7), ABCC8 (MODY12), KCNJ11 (MODY13), and APPL1 (MODY14)." (PMID 34079523, 2021). "In 33 (13%) patients, class 4–5 variants were identified in one of four genes usually considered as rarely involved in monogenic diabetes in adults, namely HNF1B (15 cases, 6.0%, among which 10 HNF1B whole-gene deletion), ABCC8 (8 cases, 3.2%), KCNJ11 (3 cases, 1.2%), and INS (7 cases, 2.8%)." (PMID 31291970, 2019). "According to the onset age, DM induced by the ABCC8 variants are classified as two major groups of disorders—ABCC8-induced nonneonatal diabetes mellitus (ABCC8-NNDM) and ABCC8-induced neonatal diabetes mellitus ABCC8-NDM." (PMID 34631896, 2021). "Furthermore the study aimed at determining whether mutations in KCNJ11, ABCC8, HNF1A, HNF4A or INS are common in AAB negative diabetes." (PMID 20863361, 2010). "Thus the search for a genetic defect in KATP (KCNJ11, ABCC8) or INS genes was justified, but the severe, non syndromic diabetes initially observed in our proband was not compatible with a loss-of-function GCK variant." (PMID 40244428, 2025).
hyperinsulinism (70 papers, 2008 to 2026). "In two patients, two distinct pathogenic variants in the ABCC8 gene were identified, consistent with the pathogenic model of obesity development under insulin resistance induced by hyperinsulinemia." (PMID 40149731, 2025). "The most common genetic cause of hyperinsulinism is gain-of-function variants in ABCC8 and KCNJ11, which make up the ATP-sensitive potassium channel (KATP)." (PMID 40605820, 2025). "KATP-channel inactivating mutations in ABCC8 associated with mutations in the KCNJ11 gene cause 97% of cases of diazoxide-unresponsive hyperinsulinism." (PMID 38791571, 2024). "It is imperative to consider genetic testing as a tool for the prevention and management of neonatal hyperinsulinism outside the context of consanguinity when one of the parents is an already known carrier of an ABCC8 mutation." (PMID 38952388, 2024). "The new variant has now been reclassified as likely pathogenic, with the sisters’ genotype therefore consistent with autosomal recessive ABCC8-associated hyperinsulinism." (PMID 39153498, 2024). "Yet, when studying SUR1 (ABCC8) polymorphisms related to infantile hyperinsulinism, it was found that the regulation of these channels includes mechanisms other than ATP control." (PMID 38612888, 2024). "Recessively inherited loss-of-function mutations in either ABCC8 or KCNJ11 are the most common cause of congenital hyperinsulinism." (PMID 38366195, 2024). "Both sisters were subsequently discovered to have novel compound heterozygous variants in the ABCC8 gene, consistent with autosomal recessive monogenic hyperinsulinism." (PMID 39153498, 2024). "Disease-causing single nucleotide variants affecting over 30 genes are known to cause persistent hyperinsulinism with mutations in the KATP channel genes (ABCC8 and KCNJ11) most commonly identified in children with severe persistent disease." (PMID 35872984, 2022). "ABCC8 encodes a beta-cell potassium channel unit and causes congenital hyperinsulinism or MODY depending on the mutation location." (PMID 36144251, 2022). "ABCC8 is highly expressed in pancreatic islet cells where it functions to release insulin, and recessive mutations cause congenital hyperinsulinemia and neonatal diabetes mellitus." (PMID 35204766, 2022). "Inactivating mutations in ABCC8 resulting in excess insulin secretion have been successfully employed for modeling congenital hyperinsulinism using ABCC8-deficient ESC." (PMID 34079523, 2021). "Recessive or compound heterozygous loss-of-function ABCC8 mutations, inactivating, causes hyperinsulinemia and hypoglycemia, whereas dominant variants cause hyperinsulinism." (PMID 34584998, 2021). "Among the 87 probands previously reported, 24% (21/87) carried inactivating ABCC8 variants reported in hyperinsulinemia, whereas 24% (21/87) carried activating ABCC8 variants were also associated with NDM." (PMID 34631896, 2021). "Pathogenic variants of ABCC8 are the most common genetic cause of neonatal diabetes and hyperinsulinism." (PMID 34113617, 2021). "Individuals with hyperinsulinism born appropriate or large for gestation and unresponsive to diazoxide treatment are most likely to have an ABCC8 or KCNJ11 mutation." (PMID 34633981, 2021). "There are at least nine different genetic subtypes of hyperinsulinism, but the most common and severe form is caused by inactivating mutations in ABCC8 or KCNJ11, the genes encoding the two component of the β-cell KATP channel." (PMID 32735622, 2020). "In conclusion, our case of diazoxide-resistant hyperinsulinism due to compound heterozygous ABCC8 mutations showed a good response to a combined treatment of nifedipine and octreotide." (PMID 26316440, 2015). "A novel combination of mutations in the ABCC8 gene leading to diffuse, diazoxide-unresponsive congenital hyperinsulinism was identified." (PMID 26180531, 2015).
hyperinsulinism (continued). "In conclusion, our case of diazoxide-resistant hyperinsulinism due to homozygous ABCC8 nonsense mutation showed a good response to a combined treatment of nifedipine and octreotide." (PMID 24932607, 2014). "Loss‐of‐function ABCC8 variants are the commonest cause of congenital hyperinsulinism." (PMID 39601258, 2025). "In the second patient, the onset was on the third day of life with severe hypoglycemia, and genetic testing identified a heterozygous mutation in the ABCC8 gene c.1792C>T (p.Arg598*) inherited on the paternal line, which led to the diagnosis of the focal form of hyperinsulinism." (PMID 38791571, 2024). "Both have previously been reported for hyperinsulinism-inducing mutations in ABCC8." (PMID 38366195, 2024). "ABCC8 variants can cause hyperinsulinemia by activating or deactivating gene expression." (PMID 38212772, 2024). "Hyperinsulinism of various severity levels is usually induced by inactivating mutations in ABCC8." (PMID 36836406, 2023). "Hyperinsulinism caused by dominant mutations in ABCC8 and KCNJ11may be milder and diazoxide-responsive, but some of the dominant defects may be as severe and diazoxide-unresponsive as hyperinsulinism caused by biallelic recessive KATP mutations." (PMID 33502730, 2021). "The identification of biallelic ABCC8 loss-of-function variants in patients with neonatal diabetes was unexpected as recessive loss-of-function K-ATP channel mutations usually cause congenital hyperinsulinism." (PMID 28663158, 2017). "Inactivating mutations in ABCC8, encoding SUR1, lead to congenital hyperinsulinism." (PMID 28951826, 2017). "Mutations in the SUR1 (ABCC8) and the Kir6.2 (KCNJ11) cause familial hyperinsulinemia in infancy, while some polymorphisms in these genes (exon 16-3t/c and exon 18 C/T of ABCC8 and E23K of KCNJ11) have been reported to be associated with T2D in several populations at different degrees." (PMID 25309595, 2014). "Our recommendation is to send genetic testing as soon as possible for the child and his/her parents, especially for the diazoxide-unresponsive cases as the detection of a single recessive paternal KATP mutation (ABCC8 or KCNJ11) has a positive predictive value of 94% for focal hyperinsulinism." (PMID 23384201, 2013). "Inactivating mutations in the genes encoding the two subunits of the ß-cell ATP-sensitive potassium channel (KATP channel), ABCC8 and KCNJ11 (encoding SUR-1 and Kir6.2, respectively), cause the most common and severe form of hyperinsulinism, although mutations in ABCC8 are more common." (PMID 23384201, 2013). "BRSK2 variant carriers may exhibit congenital hyperinsulinism due to β-cell hypersecretion, which causes a vicious cycle between hyperinsulinemia and insulin resistance, akin to the most recognized genetic variants of ABCC8 and KCNJ11 in T2DM." (PMID 37188647, 2023). "In addition, congenital hyperinsulinism caused by ABCC8 variants can develop into MODY." (PMID 35002955, 2021). "However, mutations in ABCC8 mostly result in hyperinsulinemia." (PMID 29087246, 2017). "Furthermore, some of the variants like heterozygous E1506K pathogenic variant in the ABCC8 gene resulting in congenital hyperinsulinism in infancy, loss of insulin secretory capacity in early adulthood, and autosomal dominant diabetes in middle age in different members." (PMID 28095440, 2017). "That is, this channel regulates insulin secretion in pancreatic beta cells; therefore, when mutations occur in the genes encoding SUR1 (ABCC8) and Kir6.2 (KCNJ11), serious problems in insulin secretion arise, leading to neonatal diabetes or hyperinsulinism." (PMID 41009376, 2025). "Our case involved a monogenic cause of hyperinsulinism, which affects 1/50 000 live births, with the most severe forms being caused by inactivating mutations of the ABCC8 and KCNJ11 genes (that account for 36–70% of congenital hyperinsulinism cases)." (PMID 39153498, 2024).
hyperinsulinism (continued). "Mutations in the KATP channel genes, ABCC8 and KCNJ11, are the most common cause of congenital hyperinsulinism." (PMID 34633981, 2021). "The repression of Kir6.2/SUR1 channels stimulates the release of insulin, and it has been reported that mutations and deficiencies of ABCC8 and KCNJ11 induce hyperinsulinism." (PMID 32906679, 2020). "The major treatment for congenital hyperinsulinism and neonatal diabetes patients carrying ABCC8 or KCNJ11 mutations is diazoxide (SUR1 activator)." (PMID 32882918, 2020). "Mutations in ABCC8 and KCNJ11 are the major cause of neonatal diabetes mellitus and congenital hyperinsulinism." (PMID 32882918, 2020). "Mutations in the Kir6.2 (KCNJ11 gene, omim #600937) and SUR1 (ABCC8 gene, omim #600509) subunits lead to permanent closure of the channel and account for 40–45% of all cases of congenital hyperinsulinism." (PMID 31840185, 2020). "Gain-of-function mutations in the genes encoding the Kir6.2 (KCNJ11) and SUR1 (ABCC8) subunits of the channel cause neonatal diabetes, whilst loss-of-function mutations in these genes result in congenital hyperinsulinism." (PMID 28663158, 2017). "Mutations in eight different genes (ABCC8, KCNJ11, GLUD1, CGK, HADH, SLC16A1, HNF4A and UCP2) have been identified to date in patients with congenital forms of hyperinsulinism (CHI)." (PMID 23032149, 2012). "As a result, a paternally inherited germline mutation in ABCC8 or KCNJ11 becomes “homozygous” or “hemizygous” due to the absence of the second allele leading to hyperinsulinism in the affected beta‐cells." (PMID 41438615, 2025). "LOF mutations in the ABCC8 or KCNJ11 genes lead to KATP channel dysfunction and hyperinsulinism." (PMID 38791571, 2024). "Loss-of-function mutations in either the pore-forming (inwardly rectifying potassium channel 6.2 [Kir6.2], encoded by KCNJ11) or regulatory (sulfonylurea receptor 1, encoded by ABCC8) subunits result in congenital hyperinsulinism, whereas gain-of-function mutations cause neonatal diabetes." (PMID 38366195, 2024). "In the first patient, del/dup copy number variation (CNV) analysis using the Blueprint Genetics (BpG) Hypoglycemia, Hyperinsulinism and Ketone Metabolism Panel identified a homozygous deletion, ABCC8 c.(2390+1_2391-1)_(3329+1_3330-1)del, encompassing exons 20–26 of ABCC8." (PMID 38791571, 2024). "Molecular genetic testing (Hypoglycemia, Hyperinsulinism and Ketone Metabolism Panel, Blueprint Genetics Laboratory) identified a homozygous deletion in the ABCC8 gene, c.(2390+1_2391-1)_(3329+1_3330-1)del, which encompasses exons 20–26; the result correlating with diffuse CHI." (PMID 38791571, 2024). "The most frequent genetic cause of hyperinsulinism and neonatal diabetes is pathogenic mutations in KCNJ11 and ABCC8; the subunits of the β-cell ATP-sensitive potassium channel, a crucial element of the glucose-stimulated insulin secretion pathway, are encoded by these genes." (PMID 38283146, 2023). "Mutations in ABCC8 are associated with maturity-onset diabetes of the young (MODY), neonatal diabetes, and severe congenital hyperinsulinism." (PMID 36389068, 2022). "Activating mutations in ABCC8 are known to cause neonatal diabetes, maturity onset diabetes of the young (MODY) and T2D, while loss of function mutations lead to an opposite phenotype with hyperinsulinism and hypoglycemia." (PMID 29112131, 2017). "Likewise, individuals with another partial loss-of-function ABCC8 mutation (R1353H) have been diagnosed with hyperinsulinism, gestational diabetes and non-obese antibody-negative early-onset diabetes." (PMID 38366195, 2024). "However, a genotype:phenotype correlation is not absolute since the ABCC8 p.I1512T mutation was found in another patient tested in Exeter whose hyperinsulinism remitted within a few days of birth." (PMID 27908292, 2016).
hyperinsulinism (continued). "It is therefore likely that ABCC8 and KCNJ11 are co-regulated as a result of TFAP2A-mediated chromatin looping, and that the disruption of TFAP2A binding at either locus leads to congenital hyperinsulinism." (PMID 28100260, 2017). "However, BWS patients usually do not carry pathogenic variants in either ABCC8 or KCNJ11 and the underlying mechanism responsible for hyperinsulinism in these patients is not known." (PMID 36339418, 2022).
type 2 diabetes (61 papers, 2003 to 2026). "Variants in ABCC8 have been linked to various disorders of glucose homeostasis, including hyperinsulinemic hypoglycemia and type 2 diabetes." (PMID 40981175, 2025). "Co-localisation analysis suggested that type 2 diabetes and BMI associations had a 94.0% posterior probability of sharing a causal variant in ABCC8." (PMID 37171501, 2023). "According to the OMIM database, mutations in the ABCC8 gene are associated with maturity-onset diabetes of the young (MODY_12, MIM # 125853)." (PMID 38162681, 2023). "Mutations in the ABCC8 gene cause the overactivity or underactivity of the KATP channel, and thereby, a variety of phenotypes.Previous studies suggested an association between adult-onset diabetes and mutations in the ABCC8 gene." (PMID 35992135, 2022). "In parallels with neonatal diabetes, alteration in Katp channel function also plays an etiological role in the development of type 2 diabetes with the E23K/S1119 KCNJ11/ABCC8 variants associated with a 1.32 increase in the risk of type 2 diabetes." (PMID 33693776, 2021). "We aimed to analyze a novel ABCC8 variant of a Chinese patient with suspected maturity-onset diabetes of the young (MODY) and to provide evidence for precise diagnosis and appropriate treatment." (PMID 35002955, 2021). "CRISPR targeting of non-coding DNA harboring type 2 diabetes (T2D) risk variants revealed changes in ABCC8, SIX2 and SIX3 expression, and impaired β-cell function, thereby linking regulatory elements in these target genes to T2D genetic susceptibility." (PMID 33893274, 2021). "The association between ABCC8 gene C49620T polymorphism and type 2 diabetes (T2D) in populations of diverse ethnic backgrounds has been reported." (PMID 29751826, 2018). "Mutations in the sulfonylurea receptor (SUR) 1 encoded by ABCC8 have previously been shown to cause neonatal diabetes, maturity onset diabetes of the young (MODY) and adult T2D." (PMID 25117150, 2014). "Genetically proxied inhibition of ABCC8, equivalent to a 1-unit reduction in log odds of type 2 diabetes, was significantly associated with a lower risk of LS in GIGASTROKE but not in the MRI-confirmed cohort [GIGASTROKE: OR, 0.22 (95% CI, 0.10–0.49); MRI-confirmed: OR, 0.59 (95% CI, 0.15–2.25)]." (PMID 39661645, 2025). "Activating mutations in the ABCC8 gene, which encodes the SUR1 protein, have previously been described as a cause of neonatal diabetes or maturity-onset diabetes of the young (MODY), whereas inactivating mutations in this gene usually lead to hyperinsulinemia hypoglycemia (HI) in infancy." (PMID 39556225, 2024). "Interestingly, the ABCC8 locus and specifically the variant rs3758953 in this study have been reported to be associated with type 2 diabetes, and the carriers of the risk genotypes of rs3758953 had higher levels of both glucose and insulin." (PMID 35474489, 2022). "A 44-yr-old male participant with a significant family history of both type 1 and type 2 diabetes and a personal history of insulin-dependent diabetes diagnosed at age 34 was found to have an ABCC8 variant previously reported to cause autosomal dominant hyperinsulinemia (ABCC8; MIM: 600509)." (PMID 30487145, 2018). "Thus, common variants in KCNJ11 and ABCC8 were logical selection also for pharmacogenetic studies in type 2 diabetes." (PMID 24324494, 2013). "This study investigated the association of SNPs ADRB3(rs4994), ABCC8 (rs1799854),FTO (rs8050136) and TCF7L2(rs7901695 and rs12255372) with type 2diabetes in a sample of the Amazonian population." (PMID 39133695, 2024). "We identify many genes with a well-defined role in relation to type 2 diabetes (e.g. ABCC8, SLC30A8), including 48 of the 132 type 2 diabetes effector genes from the Type 2 Diabetes Knowledge Portal." (PMID 38967666, 2024). "Module 84 contained three effector genes from the Type 2 Diabetes Knowledge Portal—ABCC8, SLC30A8, and G6PC2—and module 103 included two effector genes: PAX6 and STARD10." (PMID 37333221, 2023).